GPC4 (glypican 4)
Description:
Cell surface proteoglycan that bears heparan sulfate. May be involved in the development of kidney tubules and of the central nervous system (By similarity).
Synonyms: K-glypican; KPTS
Tractability: Antibody: its Gene Ontology location is reachable by antibodies, with high confidence; UniProt places it where antibodies can reach, with medium confidence; UniProt predicts a signal peptide or a membrane-spanning region; the Human Protein Atlas places it where antibodies can reach. PROTAC: its protein half-life has been measured.
Gene: Protein-coding gene on chromosome X (133,300,103 to 133,416,214, reverse strand). Ensembl gene ENSG00000076716.
Subcellular location: Cell membrane; Secreted, extracellular space (Secreted glypican-4)
Subcellular location (Human Protein Atlas): Plasma membrane; Nucleoplasm
Pathways (Reactome):
Disease: Attachment and Entry; Defective B3GALT6 causes EDSP2 and SEMDJL1; Defective B3GAT3 causes JDSSDHD; Defective B4GALT7 causes EDS, progeroid type; Defective EXT1 causes exostoses 1, TRPS2 and CHDS; Defective EXT2 causes exostoses 2; Dengue Virus Attachment and Entry; Dengue Virus-Host Interactions; RSV-host interactions; Respiratory syncytial virus (RSV) attachment and entry
Metabolism: Glycosaminoglycan-protein linkage region biosynthesis; HS-GAG biosynthesis; HS-GAG degradation
Hemostasis: Initiation of coagulation cascade; Regulation of clotting cascade
Sensory Perception: Retinoid metabolism and transport
Gene Ontology:
Molecular function: protein binding; coreceptor activity
Biological process: Wnt signaling pathway; cell migration; regulation of neurotransmitter receptor localization to postsynaptic specialization membrane; regulation of presynapse assembly; synaptic membrane adhesion; regulation of signal transduction
Cellular component: external side of plasma membrane; extracellular exosome; nucleus; cell surface; extracellular matrix; Golgi lumen; lysosomal lumen; plasma membrane; synapse; extracellular region; glutamatergic synapse
Homologues: Orthologues: chimpanzee GPC4 (100% identical), macaque GPC4 (99% identical), rabbit GPC4 (95% identical), mouse Gpc4 (95% identical), pig GPC4 (95% identical), dog GPC4 (94% identical), guinea pig GPC4 (94% identical), rat Gpc4 (93% identical), tropical clawed frog gpc4 (72% identical), zebrafish gpc4 (55% identical), Drosophila melanogaster dlp (37% identical). Paralogues in human: GPC6 (63% identical), GPC1 (41% identical), GPC2 (38% identical), GPC5 (24% identical), GPC3 (23% identical).
Diseases named in the same sentence as GPC4 in open-access papers:
GPC4 is named in the same sentence as 104 diseases in open-access papers, as found by Europe PMC text mining. Sharing a sentence is not in itself a finding about the gene and the disease. The quoted sentences say what the papers report.
Insulin resistance (13 papers, 2014 to 2024). Increased resistance towards insulin, that is, diminished effectiveness of insulin in reducing blood glucose levels. "Shedded GPC4 can be detected in blood also and has been linked with insulin resistance as well as with several metabolic disorders." (PMID 36353562, 2022). "These authors also stated that glypican-4 levels correlated with cardiometabolic risk factors, including insulin resistance and arterial stiffness, and the measurements were independently associated with non-alcoholic fatty liver disease, in women." (PMID 33740336, 2021). "Increased levels of glypican-4 are associated with risk of type 2 diabetes and the prevalence of insulin resistance in these patients." (PMID 33926070, 2021). "In addition, circulating Gpc4 levels had a significant positive correlation with the WHR and the ratio of visceral to subcutaneous fat area, indicating the association of Gpc4 with body fat distribution and insulin resistance." (PMID 25371737, 2014). "Of great interest is also the deficiency of GPC4 (glypican 4) found in both syndromes, which is a regulator of neuronal differentiation and a new marker characterizing neuronal cells and, on the other hand, is considered a new adipokine associated with obesity and insulin resistance." (PMID 36553637, 2022). "In conclusion, this study allows a first insight in the potential role of GPC-4 levels in insulin resistance, glucose metabolism and adiposity in pregnancy." (PMID 34903856, 2021). "When considering GPC4 as a biomarker for insulin resistance and NAFLD it is important to consider sex-specific differences as healthy men present with higher plasma GPC4 levels compared to women." (PMID 32508807, 2020). "Circulating GPC4 has been previously associated with several disorders linked to insulin resistance including elevated systolic blood pressure, non-alcoholic fatty liver disease, and kidney disease." (PMID 36353562, 2022). "Due to the association of GCP-4 with increased fasting insulin and HOMA-IR, we hypothesized an increase of GPC-4 during pregnancy due to the rising physiological insulin resistance and, potentially, a connection to GDM status." (PMID 34903856, 2021). "Since its discovery as a novel adipokine, several studies further confirmed this strong correlation using serum GPC4 levels and also identified that increased GPC4 serum levels positively associated with the prevalence of NAFLD and insulin resistance in at risk patients." (PMID 32508807, 2020). "Moreover, Chi3l1 plays an important role in insulin resistance and diabetes, which closely correlates with glypican-4 (GPC-4), neuregulin-4 (NRG4), body mass index (BMI), the waist-to-hip ratio (WHR), and homeostasis model assessment of insulin resistance (HOMA-IR) in women with PCOS." (PMID 39769202, 2024). "Indeed glypican-4 has been considered a novel adipokine that boosts insulin signaling and, interestingly glypican-4 levels are significantly increased in obese patients with insulin resistance." (PMID 30061880, 2018). "Independently of diabetes, glypican 4, clusterin, chemerin and progranulin are related with parameters of insulin sensitivity, suggesting that these adipokines may play a role in the development of insulin resistance." (PMID 24968098, 2014). "Serum glypican-4 (GPC4) has been identified as an insulin-sensitizing adipokine serving as a marker for body mass index and insulin resistance in humans." (PMID 35715556, 2022). "Further studies including normal-weight women and the addition of pre-pregnancy and postpartum GPC-4 levels would be required to shed light on the role of GPC-4 in pregnancy and insulin resistance." (PMID 34903856, 2021). "The depletion of glypican-4 reduces insulin signaling, whereas the overexpression of wild-type glypican-4 enhances the insulin-mediated phosphorylation of ERK and AKT, indicating its potential role as a target for the treatment of insulin resistance." (PMID 24633815, 2014).
Insulin resistance (continued). "No study on Glypican-4 in pregnancy and pregnancy-related insulin resistance has been published yet." (PMID 34903856, 2021).
Obesity (12 papers, 2014 to 2025). Accumulation of substantial excess body fat. "The adipokine glypican-4 (GPC-4) is a cell surface proteoglycan that has been associated with increasing obesity, diabetes mellitus, metabolic syndrome, bone development and non-alcoholic fatty liver disease (NAFLD) in previous studies." (PMID 34903856, 2021). "Hence, serum GPC-4 levels are closely associated with obesity-related parameters, implying the relatively greater importance of body fat distribution on circulating GPC-4 levels." (PMID 32467736, 2020). "Collectively, these findings underscore the important role of glypican-4 in obesity and IR, and its utility as a metabolic disorder biomarker." (PMID 40190406, 2025). "Serum glypican-4 levels have also been reported to escalate with the severity of obesity in pediatric populations aged 6 to 18 years." (PMID 40190406, 2025). "Collectively, GPC4 seems to be a potent biomarker for metabolic disease, however its exact functions in obesity development and metabolic inflammation remains to be fully established." (PMID 32508807, 2020). "Therefore, the increase in insulin in the first stages of obesity can increase the breakdown of GPC-4, the consequence of which is an increase in GPC-4 serum levels." (PMID 37151681, 2023). "GPC4 as an adipokine regulates insulin receptor signaling and thus may be associated with cardiovascular disease through obesity, but it is not known whether endothelial GPC4 expression plays a role in atherogenesis." (PMID 37511353, 2023). "The linkage between GPC4 and obesity-related traits may have contributed to the significant association between GPC4 and kidney function but does not fully explain it." (PMID 35715556, 2022). "Glypican 4 (Gpc4) may be involved in the regulation of obesity and body fat distribution." (PMID 25371737, 2014). "However, GPC4 levels have been associated with various obesity-related traits and, therefore, may not be specific to the malfunction of a particular organ." (PMID 35715556, 2022). "In addition, GPC4 may be involved in regulating obesity and body fat distribution." (PMID 31316554, 2019). "There were strong correlations of Gpc4 expression with body mass index (BMI) and waist/hip ratio (WHR) in human adipose, which indicated that Gpc4 may play an important role in obesity and body fat distribution." (PMID 25371737, 2014).
pancreatic cancer (6 papers, 2019 to 2024). "A CoxPH analysis fitted against GPC4 expression values exhibited a statistically significant association between high GPC4 levels and a poor prognosis in glioma, glioblastoma, pancreatic carcinoma, and uveal melanoma, suggesting its potential as a prognostic factor." (PMID 38612755, 2024). "Further, comprehensive bioinformatic analyses and functional in vitro experiments display a connection between downregulation of GPC4 and the sensitization of pancreatic cancer cells to chemotherapy." (PMID 38612755, 2024). "The study further reveals that the suppression of GPC4 results in the attenuation of stem cell–like properties of pancreatic cancer via suppression of the Wnt/β-catenin pathway." (PMID 38612755, 2024). "Kaplan-Meier curves reveal a statistically significant correlation between higher levels of GPC4 expression and a poor prognosis in uveal melanoma, pancreatic carcinoma, glioma, and glioblastoma cancers." (PMID 38612755, 2024). "GPC4 can activate the Wnt/β-catenin pathway and its downstream targets to increase 5-fluorouracil (5-FU) resistance and cell stemness in pancreatic cancer." (PMID 37101691, 2023). "The expression of glypican-4 (GPC4) is significantly upregulated in pancreatic cancer tissue compared with normal tissues and is remarkably correlated with overall survival, according to data from The Cancer Genome Atlas (TCGA) database." (PMID 34249755, 2021). "Knockdown of GPC4 sensitizes pancreatic cancer cells to 5-FU and inhibits stem cell–like properties by suppressing Wnt/β-catenin pathway." (PMID 31334229, 2019). "In pancreatic cancer, it’s reported targeting GPC4 could overcome 5-Fu resistance and cell stemness through suppression of Wnt/β-catenin pathway." (PMID 31484922, 2019). "Furthermore, they showed that knockdown of GPC4 also remarkably attenuated the invasive capacity of pancreatic cancer cells, suggesting that GPC4 might be an upstream regulator of pancreatic cancer stemness." (PMID 34249755, 2021). "Expression of glypicans in PANC-1 pancreatic cancer cells showed that GPC1was the most expressed, followed by GPC4 and GPC6, while GPC2 was not detectable." (PMID 34249755, 2021).
Simpson-Golabi-Behmel syndrome (6 papers, 2010 to 2025). Simpson-Golabi-Behmel syndrome is a rare X-linked multiple congenital anomalies syndrome, characterized by pre- and postnatal overgrowth, distinctive craniofacial features, variable congenital malformations, organomegaly and an increased tumor risk. "Other GPCs have been shown to play roles in diseases such as hepatocellular carcinoma (GPC3;) and Simpson-Golabi-Behmel syndrome (GPC3/GPC4;)." (PMID 32398079, 2020). "The Simpson-Golabi-Behmel syndrome (SGBS) is a X-linked overgrowth/malformation syndrome caused by mutations in GPC3 and GPC4." (PMID 20360844, 2010).
breast carcinoma (5 papers, 2021 to 2024). "Two clinical studies have already shown increased plasma levels of GPC4 in metastatic colorectal and breast cancer patients to be associated with poor patient survival, proposing its biomarker potential in these cancers." (PMID 38612755, 2024). "Contradictory results on the effects of GPC4 on cancer have been previously reported in breast cancer." (PMID 38612755, 2024). "Our in vitro cell line data show a high relative gene expression of GPC4 in the HER2 breast cancer cell lines, SKBR3 and BT-474." (PMID 33742285, 2021). "In the present study, we have found that for overall unclassified breast cancer, high levels of GPC4 showed a longer RFS." (PMID 33742285, 2021). "In summary, we have found promising results in our study suggesting the prognostic power of GPC1, GPC3, GPC6 and potentially also GPC4 expression on the survival of breast cancer patients." (PMID 33742285, 2021). "In this study, high levels of GPC4 were shown to be associated with longer relapse-free time in unclassified breast cancer, whereas in estrogen receptor negative and HER2-positive breast cancer low GPC4 levels led to a longer relapse-free time." (PMID 38612755, 2024). "We looked for experimentally supported interactions with GPC1, GPC3, GPC4, and GPC6 as these are the glypicans we found to have the highest impact on the prognosis of breast cancer patients." (PMID 33742285, 2021). "Next, GPC4, Glypican 4, a known regulator of WNT signaling, known to be downregulated in breast cancer and ovarian cancer, and upregulated in colorectal cancer was seen to be mutated in 50% of the patients." (PMID 34796107, 2021). "The basal breast cancer cell lines MDA-MB-453 and MDA-MB-468 show a similar glypican gene expression pattern, with high expression of GPC1 and GPC4 and MDA-MB-231 shows a high expression of GPC1 and GPC6." (PMID 33742285, 2021). "Both HER2 breast cancer cell lines, SKBR3 and BT-474, show similar relative gene expression levels of GPC1 and GPC4." (PMID 33742285, 2021). "In the future, GPC1, GPC3, GPC4 and GPC6 might possibly serve as a basis for the medical treatment of breast cancer patients." (PMID 33742285, 2021).
diabetes (5 papers, 2014 to 2025). "Consequently, it is limited in fully exploring the relationship between glypican-4 and the long-term risk of developing metabolic disorders such as diabetes." (PMID 40190406, 2025). "Indeed, in proteoglycans, GPC-4 is the first-identified adipokine that associates with diabetes via increasing insulin sensitivity." (PMID 32467736, 2020). "Recently, it has been focused on circulating levels of GPC-4 in different glucose metabolism status due to its notable alterations in subjects from normal glucose tolerance to patients with diabetes." (PMID 32467736, 2020). "Hence, further investigation of the acute effects of exercise training on the turnover of GPC-4 is recommended in different glucose metabolism states and diabetes." (PMID 32467736, 2020). "However, in contrast to studies on patients with type 2 diabetes mellitus, GPC-4 levels were not significantly different between women with NGT and GDM in our analysis." (PMID 34903856, 2021). "The status of GDM, in contrast to patients with type 2 diabetes mellitus, might, thus, not be the determining factor for differences in GPC-4 levels during gestation." (PMID 34903856, 2021).
colorectal cancer (4 papers, 2020 to 2025). A primary or metastatic malignant neoplasm that affects the colon or rectum. "Conversely, CD36 acts as a tumor suppressor and inhibits aerobic glycolysis by promoting GPC4 ubiquitination and inhibiting β‐catenin/c‐myc signaling in colorectal cancer." (PMID 41267927, 2025). "A recent study described activation of Wnt/β-catenin/c-Myc signaling axis by one of the transmembrane GPI-anchored proteoglycan glypican-4 (GPC4), and the resulting up-regulation of glycolysis in colorectal cancer." (PMID 33330449, 2020). "For example, in colorectal cancer, CD36 promoted GPC4 ubiquitination via proteasome-dependent pathway and exerts inhibitory effects on glycolysis through the β-catenin-c-MYC signaling pathway." (PMID 40083702, 2025).
Impaired glucose tolerance (4 papers, 2021 to 2025). An abnormal resistance to glucose, i.e., a reduction in the ability to maintain glucose levels in the blood stream within normal limits following oral or intravenous administration of glucose. "In concordance with prior research, serum glypican-4 levels were significantly elevated in individuals with impaired glucose tolerance." (PMID 40190406, 2025). "It has been reported that serum levels of GPC-4 increase in pre-diabetic subjects with impaired glucose tolerance, but decrease in newly diagnosed T2DM patients." (PMID 37151681, 2023). "Circulating glypican-4 levels are higher in subjects with impaired glucose tolerance and positively correlated with BMI, WHR and HOMA index." (PMID 33740336, 2021). "Furthermore, circulating glypican-4 levels are higher in subjects with impaired glucose tolerance and positively correlated with BMI and WHR, the Homeostasis Model Assessment (HOMA) index." (PMID 33740336, 2021).
Keipert syndrome (4 papers, 2021 to 2023). "Defects in glypicans, a group of heparan sulfate proteoglycans (HSPGs), can cause abnormal skull and skeletal dysplasia in both humans (Simpson–Golabi–Behmel syndrome: glypican 3, GPC3; Keipert syndrome: glypican 4, GPC4) and zebrafish (Knypek: Gpc4)." (PMID 34595172, 2021).
metabolic syndrome (4 papers, 2021 to 2025). A cluster of metabolic risk factors for CARDIOVASCULAR DISEASES and TYPE 2 DIABETES MELLITUS. "Additionally, in women with PCOS presenting metabolic risk factors, higher glypican-4 levels were associated with established cardiovascular disease predictors, including IR, hyperglycemia, hypertension, and dyslipidemia, with a notable emphasis on adipose tissue distribution." (PMID 40190406, 2025). "Glypican-4 belongs to a group of poorly understood adipokines, with potential importance in people with metabolic syndrome, especially in groups of patients with glucose metabolism disorder." (PMID 39062482, 2024). "This study aimed to assess the effect of physical activity on serum glypican-4 and irisin levels and total antioxidant status (TAS) in plasma and saliva in women with metabolic syndrome (MetS)." (PMID 39062482, 2024). "A recent adult study demonstrated that individuals with metabolic syndrome (MetS) exhibited significantly elevated serum glypican-4 levels when contrasted with those of healthy and non-MetS counterparts." (PMID 40190406, 2025). "Thus, this study’s main aim was to assess the effect of physical activity on serum glypican-4 and irisin levels and total antioxidant status (TAS) in plasma and saliva in women with and without metabolic syndrome (MetS)." (PMID 39062482, 2024).
non-alcoholic fatty liver disease (4 papers, 2021 to 2025). "Elevated serum glypican-4 levels have also been observed in women with nonalcoholic fatty liver disease, indicative of its hepatic involvement in MetS." (PMID 40190406, 2025).
type 2 diabetes (4 papers, 2021 to 2024). "Since no research has yet investigated the effect of resistance training with hawthorn extract on the levels of glycemic indices, GPLD1 and GPC-4 in type 2 diabetic rats induced by high fat diet-streptozotocin (HFD -STZ), this study was designed." (PMID 37151681, 2023).